RN7SKP88 (RN7SK pseudogene 88)
Gene: Miscellaneous RNA gene on chromosome 1 (148,839,483 to 148,839,732, reverse strand). Ensembl gene ENSG00000252656.
Homologues: Orthologues: mouse Gm55242 (40% identical). Paralogues in human: 7SK (100% identical), 7SK (99% identical), RN7SKP192 (63% identical), RN7SKP75 (60% identical), RN7SKP208 (59% identical), RN7SKP151 (59% identical), RN7SKP71 (59% identical), RN7SKP72 (59% identical), RN7SKP236 (58% identical), RN7SKP79 (58% identical), RN7SKP174 (58% identical), RN7SKP246 (58% identical), and 284 more.